TPD52L2 (TPD52 like 2)
Synonyms: hD54; D54; TPD54
Tractability: PROTAC: ubiquitination databases record sites on it; its protein half-life has been measured.
Gene: Protein-coding gene on chromosome 20 (63,865,228 to 63,891,545, forward strand). Ensembl gene ENSG00000101150.
Subcellular location (Human Protein Atlas): Vesicles; Cytosol
Gene Ontology:
Molecular function: protein binding; RNA binding
Biological process: carbohydrate metabolic process
Cellular component: cytoplasm
Genetic constraint (gnomAD): Loss-of-function variants: 20 observed, 25.54 expected, observed/expected ratio (o/e) 0.78, 90% interval 0.55 to 1.14. The upper end of that interval is the gene's LOEUF score, 1.14, which puts it in group 4 of 6, group 1 being the genes least tolerant of losing a copy. Missense variants: 236 observed, 256.84 expected, observed/expected ratio (o/e) 0.92, 90% interval 0.82 to 1.02. Synonymous variants: 104 observed, 102.47 expected, observed/expected ratio (o/e) 1.01, 90% interval 0.87 to 1.2.
Homologues: Orthologues: chimpanzee TPD52L2 (99% identical), mouse Tpd52l2 (91% identical), rat Tpd52l2 (91% identical), dog TPD52L2 (90% identical), pig TPD52L2 (88% identical), macaque TPD52L2 (87% identical), tropical clawed frog tpd52l2 (68% identical), zebrafish tpd52l2b (67% identical), zebrafish tpd52l2a (48% identical), Caenorhabditis elegans F13E6.1 (33% identical), Drosophila melanogaster CG5174 (31% identical). Paralogues in human: TPD52 (45% identical), TPD52L1 (43% identical), TPD52L3 (35% identical).
Diseases named in the same sentence as TPD52L2 in open-access papers:
TPD52L2 is named in the same sentence as 45 diseases in open-access papers, as found by Europe PMC text mining. Sharing a sentence is not in itself a finding about the gene and the disease. The quoted sentences say what the papers report.
breast carcinoma (8 papers, 2012 to 2025). "First, we analyzed the expression profile of ten transcript variants of tpd52l2 in different cancer types from 33 cohorts of TCGA dataset via hierarchical clustering and verified two predominantly expressed transcript variants, V5 and V6, in breast cancer and several other cancer types." (PMID 36071863, 2022). "In this study, we evaluated TPD52L2 expression and its impact on patient outcomes in a breast cancer cohort from The Cancer Genome Atlas (TCGA) dataset." (PMID 36071863, 2022). "In the present study, we utilized a two-step process to investigate the functional protein isoform of TPD52L2 in breast cancer." (PMID 36071863, 2022). "We found that TPD52L2 was highly expressed in the 1092 patients with primary breast cancer from TCGA BRCA cohort, with a median expression value of 6.177." (PMID 36071863, 2022). "Conversely, in breast cancer models, TPD52L2 suppression confers metformin resistance through Pyruvate Dehydrogenase (PDH) inhibition, attenuating mitochondrial oxidative phosphorylation and ROS generation, indicating its predictive value for the metformin response." (PMID 40973691, 2025). "In our study, TPD52L2 gene expression was also proven to be closely associated with the efficacy and outcome of radiation therapy, as breast cancer patients with low TPD52L2 levels had longer survival times after radiation therapy, as well as target therapy, than those with high TPD52L2 levels." (PMID 36071863, 2022). "We then analyzed whether TPD52L2 expression was correlated with the prognosis of breast cancer patients in the BRCA cohort." (PMID 36071863, 2022). "The proteomic dataset showed the elevated expression of tumour protein D53 (hD53 encoded by TPD52L1) and tumour protein D54 (hD54 encoded by TPD52L2) of MCF-7 breast cancer cells in response to the change of extracellular zinc, which explains to some extent why zinc promotes breast cancer growth." (PMID 38249992, 2024). "In contrast, most of the other potential targets of miR-660-5p, including VDAC1, TPD52L2, and YTHDF1, play oncogenic roles in breast cancer." (PMID 39709500, 2024).
prostate carcinoma (7 papers, 2019 to 2025). A carcinoma that arises from epithelial cells of the prostate gland. "Indeed, TPD52L2 is highly expressed in lung adenocarcinoma, oral squamous cell carcinoma, and prostate cancer." (PMID 40973691, 2025). "In addition, TPD52L2 was also reported to regulate proliferation, apoptosis, and vehicle trafficking in a variety of tumors, including glioma, pancreatic adenocarcinoma, prostate cancer, and glioblastoma." (PMID 34744715, 2021). "Other family members, such as TPD53 (also known as TPD52L1), TPD54 (TPD52L2), and TPD55 (TPD52L3), have been reported to be highly expressed in ovary, testis, colon, and prostate cancer, as well as in brain tumors, lymphoma, and leukemias." (PMID 34217360, 2021).
glioma (6 papers, 2008 to 2025). A benign or malignant brain and spinal cord tumor that arises from glial cells (astrocytes, oligodendrocytes, ependymal cells). "TPD52L2 has been extensively associated with several malignancies including gliomas." (PMID 28938569, 2017). "A previous study demonstrated that knockout of TPD52L2 inhibits glioma cell proliferation by arresting cells in the G0/G1 phase." (PMID 34744715, 2021). "A former study identified that miR-485-5p served as an anti-tumor role in glioma, and miR-485-5p overexpression glioma tumorigenesis by repressing the expression of its target gene TPD52L2." (PMID 34627193, 2021). "CLTA and TPD52L2 had clear, verifiable glioma-specific splicing patterns by both exon array and RT-PCR; they were also listed in one of these reports." (PMID 18474104, 2008). "Furthermore, the TPD52L2 expression inhibition inhibited cell proliferation, migration, and invasion in glioma cell lines." (PMID 35087592, 2022). "Furthermore, it has been reported that TPD52L2 knockout in glioma cells suppresses their growth rate." (PMID 35087592, 2022). "For example, the evaluated expression of TPD52L2 could accelerate the proliferation and invasiveness of glioma cells by regulating WNT signaling, which provides a theoretical basis for the application of new medicine in tumor targeted therapy." (PMID 34744715, 2021). "In total, we confirmed 14 genes with glioma-specific splicing; seven were novel events identified by the exon expression array (A2BP1, BCAS1, CACNA1G, CLTA, KCNC2, SNCB, and TPD52L2)." (PMID 18474104, 2008).
lung adenocarcinoma (5 papers, 2021 to 2025). A carcinoma that arises from the lung and is characterized by the presence of malignant glandular epithelial cells. "Most recently, a detailed bioinformatic analysis revealed the oncogenic role of TPD52L2 in lung adenocarcinoma and demonstrated that its high expression is associated with immune infiltration and tumor immunosuppressive status, further supporting our results." (PMID 36071863, 2022). "TPD52L2, a member of the TPD52 family, can be used to predict the prognosis of lung adenocarcinoma, and DNAJB1 is also one of the diagnostic and prognostic markers of pancreatic cancer." (PMID 36010914, 2022).
childhood leukemia (2 papers, 2012 to 2025). An acute or chronic leukemia that occurs during childhood. "In particular, TPD52L2 may be a marker of acute lymphoblastic leukemia, and TPD52 and TPD52L2 are frequently coexpressed in childhood leukemia." (PMID 40973691, 2025).
clear cell renal cell carcinoma (2 papers, 2023 to 2025). "Overall, the results suggest that the abnormally high expression of TPD52L2 can promote the malignant phenotype of renal clear cell carcinoma cells, which further validates our bioinformatics analysis results." (PMID 38074636, 2023). "However, the role of TPD52L2 in the pathological process of clear cell renal cell carcinoma (ccRCC) is unclear." (PMID 38074636, 2023). "To determine whether TPD52L2 affects the malignant biological behavior of ccRCC cell lines, we first confirmed the relative upregulation of TPD52L2 expression in the renal clear cell carcinoma cell line 786-O using RT-qPCR." (PMID 38074636, 2023).
gastric cancer (2 papers, 2022 to 2025). A primary or metastatic malignant neoplasm involving the stomach. "The results suggested that TPD52L2 may cause the resistance of gastric carcinoma cells to chemotherapy and propose a new therapeutic target for treating gastric carcinoma cells." (PMID 35087592, 2022). "Taken together, these collective results establish TPD52/TPD52L2 as critical regulators of GC cell proliferation in vitro, suggesting their potential as therapeutic targets for gastric cancer intervention​." (PMID 40973691, 2025). "In the existing study, we found the elevated expression level of PERK, GRP78, CHOP, and IRE1α in TPD52L2 knockdown OXA-resistant gastric carcinoma cells, as compared with the control siRNA-transfected cells." (PMID 35087592, 2022). "The results demonstrated TPD52L2 upregulation in gastric carcinoma cells (resistant to OXA) which suggests that TPD52L2 has a potential role in OXA resistance chemotherapy in gastric carcinoma." (PMID 35087592, 2022). "The main objective of this study is to evaluate the TPD52L2 effect in OXA-resistant gastric carcinoma cells in vitro." (PMID 35087592, 2022). "Our earlier in vitro studies have shown that the silencing of TPD52L2 expression inhibited the growth and development of gastric carcinoma cells and colony formation." (PMID 35087592, 2022). "In the existing study, we identified that TPD52L2 contributes to the resistance of gastric carcinoma cells to OXA and explores the significant molecular mechanism in the regulation of chemoresistance." (PMID 35087592, 2022). "ER stress might be involved in TPD52L2 knockdown-induced apoptosis in OXA-resistant gastric carcinoma cells." (PMID 35087592, 2022). "We identified that the induction in caspase-3 and PARP-1 activation via TPD52L2 silencing might be a reason for the apoptotic-induced antitumor effect in gastric carcinoma cells (OXA resistant)." (PMID 35087592, 2022). "Together, these findings suggest that TPD52L2 knockdown in SGC-7901-OXA and MGC-803-OXA cells cause cell death that might be correlated with the inhibition of gastric carcinoma cell proliferation (OXA resistant)." (PMID 35087592, 2022). "However, the TPD52L2 function in the gastric carcinoma oxaliplatin (OXA) resistance remains elusive." (PMID 35087592, 2022). "Hence, the underlined results suggested that TPD52L2 knockdown blocks OXA resistance and colony formation of gastric carcinoma cells in vitro." (PMID 35087592, 2022). "However, the TPD52L2 high expression and its correlation with the increasing resistance of chemotherapeutic drugs against gastric carcinoma remain elusive." (PMID 35087592, 2022). "Overexpression & prognosis: TPD52/TPD52L2 are overexpressed in gastric cancer (GC) and are correlated with advanced TNM stages and poor survival." (PMID 40973691, 2025). "In the meantime, we investigated the TPD52L2 upregulation in OXA-resistant gastric carcinoma cells, as compared with OXA-sensitive parental cells which suggest its oncogenic role in gastric carcinoma OXA chemoresistance." (PMID 35087592, 2022). "In summary, we revealed that the elevated expression level of TPD52L2 in OXA-resistant gastric carcinoma cells and TPD52L2 knockdown reduced the viability of cells and colony-forming ability in OXA-resistant gastric carcinoma cells." (PMID 35087592, 2022).
acute myeloid leukemia (1 paper, 2025). Acute myeloid leukemia (AML) is a group of neoplasms arising from precursor cells committed to the myeloid cell-line differentiation. "TPD52L2 is the gene that encodes the protein known as tumor protein D54, which is a biomarker for breast tumors, different types of carcinomas, and lymphoid and acute myeloid leukemia." (PMID 41317544, 2025).
endometrial cancer (1 paper, 2023). Primary or metastatic malignant neoplasm involving the endometrium (mucous membrane that lines the endometrial cavity). "Tumour protein D54 (TPD52L2) had a threefold higher concentration in endometrial cancer compared to controls while the molecular chaperone endoplasmin (HSP90B1) had a threefold lower concentration." (PMID 36807337, 2023).
hepatocellular carcinoma (1 paper, 2022). A malignant tumor that arises from hepatocytes. "TPD52L2 (tumor protein D52 like 2) regulates the proliferation of hepatocellular carcinoma cells by interacting with ATP binding cassette protein." (PMID 36276981, 2022).
lymph node metastasis (1 paper, 2022). "Furthermore, higher TPD52L2 expression was significantly predictive of worse clinical outcome in lymph node-positive patients with BLBC, indicating a potential relationship between TPD52L2 and malignancies with lymph node metastasis." (PMID 36071863, 2022).
meningioma (1 paper, 2017). A generally slow growing tumor attached to the dura mater. "However, the role of TPD52L2 is not well established and its clinical relevance in context to meningioma needs to be substantiated." (PMID 28938569, 2017).
mesothelioma (1 paper, 2021). A usually malignant and aggressive neoplasm of the mesothelium which is often associated with exposure to asbestos. "As for tumor cell lines, we found that TPD52L2 expression was highest in mesothelioma (MESO) cell lines using data from the CCLE database." (PMID 34744715, 2021).
neuroblastoma (1 paper, 2010). Neuroblastoma (NB) is the most common solid, extracranial childhood tumor. "Notably, we compared the presence of the specific cassette exons in RNA from normal brain and neuroblastoma (for ATP6v0A1, STRADA, PCNP and CS) and from skeletal muscle and rhabdomyosarcoma (for TPM3, TPD52L2, NAP1L1, METT10 D and SLC25A3)." (PMID 20813049, 2010).
sarcoma (1 paper, 2021). A usually aggressive malignant neoplasm of the soft tissue or bone. "To assess TPD52L2 expression only in tumor tissues, we observed that TPD52L2 was highest in sarcoma (SARC) and lowest in LIHC." (PMID 34744715, 2021).
cancer (15 papers, 2017 to 2025). A tumor composed of atypical neoplastic, often pleomorphic cells that invade other tissues. "Tumor protein D52-like 2 or simply TPD52L2 belongs to the TPD52 family which has been implicated in a variety of human carcinomas." (PMID 35087592, 2022). "To corroborate and expand the results, we investigated whether V5 or V6 was required to rescue the functional loss of TPD52L2 and to maintain the cancer-related phenotypes." (PMID 36071863, 2022). "To this end, we collected data on TKIs-targeted drugs in ccRCC treatment through the NCI-60 cancer cell line database and compared the expression of TPD52L2 with drug sensitivity." (PMID 38074636, 2023). "TPD52L2 knockdown suppresses tumor growth, and V6 correlates with cancer-related phenotypes in BLBC." (PMID 36071863, 2022). "TPD52L2 is a protein that contributes significantly to tumorigenesis and various kinds of carcinomas." (PMID 35087592, 2022). "TPD52L2, a member of the TPD52-like protein family, is highly expressed and linked to poor prognosis in several types of cancers." (PMID 34744715, 2021). "To evaluate the prognostic significance of TPD52L2 in pan-cancer, we performed the Kaplan–Meier analysis and uniCox." (PMID 34744715, 2021). "As the investigations indicated, TPD52L2 is a regulator in cell cycle and played an essential role in the cell growth for many cancer types." (PMID 31240215, 2019). "Due to the association of V6 expression and patient prognosis after radiation therapy or targeted therapy in SKCM and MESO datasets, we recommend that further studies address whether TPD52L2 plays a similar malignancy-related role in other cancer types." (PMID 36071863, 2022). "Although TPD52L2 is upregulated in multiple cancers, little is known about its roles in BLBC." (PMID 36071863, 2022). "TPD52L2 was reported to regulate proliferation and apoptosis in cancer cells." (PMID 34744715, 2021). "In our study, we comprehensively analyzed the role of TPD52L2 using pan-cancer data from TCGA database in 33 cancers, including expression, prognostic values, DNA methylation, copy number alteration (CNA), and mutation status of TPD52L2." (PMID 34744715, 2021). "As a result, the The Cancer Immunome Database (TCIA) database was used to examine the IPS scores of the various TPD52 and TPD52L2 expression groups." (PMID 40973691, 2025). "Utilizing The Cancer Genome Atlas (TCGA), Gene Expression Omnibus (GEO), and tissue microarray datasets, we analyzed TPD52/TPD52L2 expression patterns in patients with GC." (PMID 40973691, 2025).